DEFB1 (defensin beta 1)
Diseases named in the same sentence as DEFB1 in open-access papers (continued):
Sharing a sentence is not in itself a finding about the gene and the disease.
oral cancer (5 papers, 2012 to 2022). "Similarly, hBD-1 overexpression by stable transfection of DEFB1 has also been shown to inhibit migration of several oral cancer cell lines (HSC-3, UM1, SCC-9 and SCC-25)." (PMID 31131258, 2019). "The top 3 IRGPs most strongly and positively correlated with the outcome of oral cancer were TNFRSF12A|TNC, PLAU|DEFB1, and TAP|IGHG2." (PMID 35804390, 2022).
renal carcinoma (5 papers, 2014 to 2022). A carcinoma arising from the epithelium of the renal parenchyma or the renal pelvis. "Human beta-defensin-1 (DEFB1) has been reported to be a potential tumor suppressor in prostate and renal cancer." (PMID 35804390, 2022). "Overexpression of hBD-1, by stable transfection of DEFB1 cDNA in renal cancer cells (SW156) resulted in caspase-3-mediated apoptosis." (PMID 31131258, 2019).
chorioamnionitis (4 papers, 2006 to 2018). A morphologic finding indicating inflammation of the fetal sac membranes. "MBL-2 presumably functions as part of the host defense system, including DEFB1, which prevents or limits infections that cause chorioamnionitis and PPROM." (PMID 30290772, 2018).
periodontal disease (4 papers, 2012 to 2024). "The objective of this study was to examine whether, among individuals with PKU and T1DM, those with IL1B rs1143634 and/or DEFB1 rs11362 exhibit a higher susceptibility to the development of periodontal disease compared to healthy controls." (PMID 38248068, 2024).
cholestasis (3 papers, 2018 to 2026). Impairment of the bile flow caused by obstruction within the liver, or outside the liver in the bile duct system. "In the present study, DEFB1 was > eight-fold induced; however, serum markers of cholestasis were either insignificantly increased or even repressed, and the observed inhibition of CYP7A has major implications on bile acid synthesis and bile pool size." (PMID 36674967, 2023). "Moreover, a recent study reported DEFB1 to be induced during cholestasis, with bilirubin and bile acids modulating its expression." (PMID 36674967, 2023).
gastritis (3 papers, 2010 to 2023). Inflammation of the stomach. "Also, an analysis of single nucleotide polymorphisms in the DEFB1 gene correlated patients with chronic active H. pylori-induced gastritis with the SNP G-52A, suggesting an involvement of the constitutive expressed hBD-1 in susceptibility to this form of gastritis." (PMID 21151692, 2010).
infertile (3 papers, 2017 to 2020). "Studies have confirmed the expression of β-defensin genes (including DEFB1) in human, rat and ram epididymis, and Male mice with β-defensin gene knock-out were reported to be infertile." (PMID 32053710, 2020). "We further examined DEFB1-induced motility in infertile spermatozoa from asthenozoospermia patients, who had lowered level of DEFB1." (PMID 29207656, 2017). "To confirm that the currents induced by DEFB1 and CCL20 were genuinely mediated by CatSper channel, we performed patch-clamp experiments on sperm samples donated by an infertile male who carries a G to C mutation of CatSper2 in one allele and complete absence of CatSper2 in the other allele." (PMID 29207656, 2017).
lung adenocarcinoma (3 papers, 2015 to 2026). A carcinoma that arises from the lung and is characterized by the presence of malignant glandular epithelial cells. "Overall, our study identifies DEFB1 as a novel driver of lung adenocarcinoma, and the anti-DEFB1 monoclonal antibody mAb-5 emerges as a promising therapeutic candidate with significant potential." (PMID 42009648, 2026).
oral diseases (3 papers, 2014 to 2025). "Certain beta-defensin 1 (DEFB1) gene variants may be linked to oral diseases." (PMID 41195299, 2025). "Background and objective: Some variants in defensin beta 1 (DEFB1) and mannose-binding lectin 2 (MBL2) genes can be associated with oral diseases." (PMID 36832361, 2023).
acne (2 papers, 2019 to 2024). An inflammatory process of the sebaceous glands which is characterized by comedones, nodules, papules and/or pustules on the skin. "Increased expression of DEFB1, DEFB2, and DEFB4 is observed in acne lesions, indicating that defensins play a role in host defense mechanism against microbial pathogens in acne." (PMID 31281837, 2019).
depression (2 papers, 2018 to 2020). "Beta-defensing 1 encoded by the DEFB1 gene is an antimicrobial gut mucosal protein associated with innate immunity and bacterial infection-induced inflammation—both of which have been associated with depression." (PMID 33510640, 2020). "While these SNPs were not genome-wide significant, functional studies, as described subsequently, demonstrated that both DEFB1 and AHR played important roles in mediating inflammatory pathways that are involved in depression." (PMID 33510640, 2020).
fungal infections (2 papers, 2018 to 2019). "We highlighted the beta-defensin genes (DEFB1, DEFB4A, DEFB5, DEFB6, DEFB7, DEFB10, and DEFB13) that encode host defense peptides that are critical to protection against bacterial, viral and fungal infections, and acts as an important link between innate and adaptive immune responses." (PMID 30223795, 2018).
head and neck cancer (2 papers, 2012 to 2021). A primary or metastatic malignant neoplasm affecting the head and neck. "Polymorphisms in the DEFB1 gene that encodes hBD-1 have been associated with increased susceptibility to HPV infection, whilst SLPI is known to have potent anti-viral activity against HPV in head and neck cancers and is upregulated in CIN and cervical cancer." (PMID 34736529, 2021).
melanoma (2 papers, 2020 to 2024). A malignant, usually aggressive tumor composed of atypical, neoplastic melanocytes. "Our study demonstrated for the first time, an aberrant expression of DEFB1 in melanoma compared to normal skin." (PMID 32719391, 2020). "On the other hand, though identified as a tumor suppressor gene by previous research, DEFB1 might play a different role in melanoma than other types of cancer, which could potentially fuel mechanistic research on its unfavorable role in melanoma." (PMID 32719391, 2020). "Taken together, DEFB1 is indicative of patient survival and is a potential biomarker in melanoma." (PMID 32719391, 2020).
type 1 diabetes (2 papers, 2024). "Similarly, long-chain, but not short-chain, inulin-type fructans delayed the onset of type 1 diabetes by promoting gut health, including a significant increase in Defb1 and Camp in the colon of mice." (PMID 39053604, 2024).
allergic asthma (1 paper, 2019). A asthma with a basis in a pathological type I hypersensitivity reaction. "In contrast to CF in which DEFB1 is inactive, allergic asthma may suppress DEFB1 secretion and increase colonization by bacterial pathogens and the risk of infection." (PMID 31881038, 2019). "Although DEFB1 is an integral part of the innate immune defense system, other components should be investigated for their role in defenses against bacterial invasions, especially in allergic asthma." (PMID 31881038, 2019).
atopic dermatitis (1 paper, 2023). "The mRNA expression of β-defensin-1 (Defb1) and Defb2 was upregulated by calcitriol treatment in NC/Nga mice with atopic dermatitis." (PMID 37298299, 2023). "Calcitriol increased the expression of Defb14 and tended to elevate that of Defb1 (p = 0.0695) in NC/Nga mice without atopic dermatitis, but it failed to elevate the expression of Defb2, Defb3, and Camp." (PMID 37298299, 2023).
bronchiectasis (1 paper, 2013). Segmental, irreversible dilation of the bronchial tree resulting in the accumulation of secretions which leads to obstruction. "Given growing evidence that DEFB1, the gene encoding HBD1, is a putative tumor suppressor whose down-regulation may be involved in tumorigenesis of multiple tissues, it is tempting to speculate that HBD1 suppression may contribute to As-induced carcinogenesis or bronchiectasis." (PMID 24004508, 2013).
cholangiocarcinoma (1 paper, 2020). A carcinoma that arises from the intrahepatic biliary tree (intrahepatic cholangiocarcinoma) or from the junction, or adjacent to the junction, of the right and left hepatic ducts (hilar cholangiocarcinoma). "Genes elevated in cholangiocarcinomas included higher expression of the cholangiocyte gene Beta‐defensin 1 (DEFB1) and FGFR2." (PMID 33332768, 2020).
cholera (1 paper, 2024). "For example, entinostat, a benzamide HDAC inhibitor, potently enhanced DEFB1 and CAMP mRNA expression in intestinal epithelial cells and protected rabbits from experimental cholera." (PMID 39053604, 2024).
chronic rhinosinusitis (1 paper, 2025). Chronic form of sinusitis. "Patient #6 (chronic rhinosinusitis), who achieved clinical improvement, showed a profile of immune resolution characterized by concurrent downregulation of GDF15 and DEFB1, signaling a return to homeostasis." (PMID 41516055, 2025).
colon adenocarcinoma (1 paper, 2015). "Glucose has been described as an APE of DEFB1 in human embryonic kidney HEK-293 and colon adenocarcinoma cells HCT-116 but not for keratinocytes." (PMID 25815330, 2015).
colonic disease (1 paper, 2012). "After multivariate analysis, only IL23R and DEFB1 remained associated with colonic disease." (PMID 23300620, 2012).
E. coli infection (1 paper, 2019). "Similar to earlier studies, E. coli infection did not upregulate the secretion of DEFB1 significantly." (PMID 31881038, 2019).
endotoxemia (1 paper, 2024). "Supplementation of inulin to a Western-style diet increased the expression of multiple Paneth cell DEFAs and DEFB1 as well as tight junction proteins in the intestinal tissues of mice, resulting in improved intestinal barrier integrity and reduced endotoxemia." (PMID 39053604, 2024).
gastric cancer (1 paper, 2012). A primary or metastatic malignant neoplasm involving the stomach. "Thus, it is possible that some variants in DEFA6 and DEFB1 affect the susceptibility to gastric cancer by modifying the inflammatory response through changes in the expression or function of those proteins." (PMID 23028900, 2012). "In conclusion, our findings suggest DEFA6, DEFB1, and INSL3 genetic variants are susceptibility factors for the development of gastric cancer." (PMID 23028900, 2012). "Our findings suggest that DEFA6 rs2738120 (located in the intron) and DEFB1 rs2702829 (located in the 3′ of STP) have potential genetic effects on the development of gastric cancer." (PMID 23028900, 2012). "Four SNPs had no heterogeneity across the phases: in the meta-analysis, DEFA6 rs13275170 and DEFB1 rs2738169 had both a 1.3-fold increased odds ratio (OR) for gastric cancer (95% CIs = 1.1–1.6; and 1.1–1.5, respectively)." (PMID 23028900, 2012). "In the Replication genotyping phase with more case-control sets and in the meta- and pooled analyses, DEFA6, DEFB1, and INSL3 were still significantly associated with gastric cancer risk without heterogeneity across the phases." (PMID 23028900, 2012).
genital warts (1 paper, 2021). "Polymorphisms in the DEFB1 gene that encodes hBD-1 have been associated with increased susceptibility to HPV infection, and upregulated hBD-1 expression has been observed in low-risk HPV-mediated genital warts." (PMID 34736529, 2021).
human papillomavirus infection (1 paper, 2018). "Further, gene polymorphism of DEFB1 has been suggested to be involved in susceptibility to human papillomavirus infection." (PMID 29736603, 2018).
localized scleroderma (1 paper, 2023). Localized scleroderma is the skin localized form of scleroderma characterized by fibrosis of the skin causing cutaneous plaques or strips. "DEFB1 transcription decreased in localized scleroderma compared to normal skin." (PMID 36830272, 2023). "Prior to treatment, DEFB1, DEFB4B, and DEFB103A transcription levels were higher in localized scleroderma compared to normal skin." (PMID 36830272, 2023).
Obesity (1 paper, 2022). Accumulation of substantial excess body fat. "However, DB decreased (concentration effect: P < 0.05) DEFB1 mRNA expression and tended to decrease (concentration effect: P = 0.05) DEFB4A mRNA expression in patients with obesity but not in lean individuals." (PMID 34784295, 2022).
oncocytoma (1 paper, 2017). "The chRCC and oncocytoma samples displayed almost identical gene expression profiles for MAL, TMEM255A, RHCG, ATP6V0A4, STAP1, and DEFB1, as demonstrated by both RNA microarray and RNA sequencing, which is in agreement with the known fact that chRCC and oncocytoma are related neoplasms." (PMID 29208006, 2017).
oral candidiasis (1 paper, 2009). Infection of the mucosal lining of the mouth with the fungus Candida albicans. "The G allele of the -44 DEFB1 SNP is associated with higher constitutive levels of both hBD1 and hBD3 in keratinocytes in a manner that is consistent with protection from oral candidiasis." (PMID 19712472, 2009).
scleroderma (1 paper, 2015). Scleroderma is a rare autoimmune connective tissue disorder characterized by abnormal hardening of the skin and, sometimes, other organs. "These suggest that in scleroderma lesions the potential of this APE could be affected by an alteration of DEFB1 overexpression pathways probably due to a unbalanced cytokine expression profile." (PMID 25815330, 2015).
serous ovarian cancer (1 paper, 2023). "The results showed that the expression of SST and DEFB1 was higher in serous ovarian cancer tissues, while the expression of the other six genes was lower in tumor tissues." (PMID 37318692, 2023).
skin infection (1 paper, 2015). An inflammatory process affecting the skin, caused by bacteria, viruses, parasites, or fungi. "Our results suggest an impact of intracellular glucose deficiency in susceptibility to skin infections due to DEFB1 downregulation, for example, ulcers in diabetic patients." (PMID 25815330, 2015).
staphylococcal infection (1 paper, 2024). An infection caused by Staphylococcus. "Knockout mice (Defb1-knock out), which no longer produce homologous murine defensin 1 (DEFb1), showed delayed bacterial clearance of the lung and increased staphylococcal infection in the bladder." (PMID 39452248, 2024).
steatosis (1 paper, 2025). Increased lipid within the cytoplasm of cells. "Afamin (AFM), angiotensinogen (AGT), β-defensin 1 (DEFB1), and PRAP1 were correlated with steatosis; DEFB1 was correlated with the NAS; and 90 proteins were associated with hepatocyte ballooning." (PMID 40250425, 2025).
teratoma (1 paper, 2017). A non-seminomatous germ cell tumor characterized by the presence of various tissues which correspond to the different germinal layers (endoderm, mesoderm, and ectoderm). "We also investigated DEFB1, DEFB3, DEFB7, and SMAD3, which may be related to teratoma formation." (PMID 28257460, 2017).
tuberculosis (1 paper, 2024). A chronic, recurrent infection caused by the bacterium Mycobacterium tuberculosis. "To further demonstrate the anti-tuberculosis effect of hBD1 in vivo, we constructed Defb1−/− mice in which the gene coding the murine counterpart of hBD1 was knocked out." (PMID 38397085, 2024). "Conversely, cells lacking hBD1 expression or mice with the Defb1 knockout exhibited significantly weakened anti-tuberculosis effects, highlighting the potential of hBD1 as an adjunctive anti-tuberculosis agent." (PMID 38397085, 2024). "Considering the consistency between CEBPB and DEFB1 expression, we hypothesized that promoting AMP expression might be one of the ways in which CEBPB exerts its anti-tuberculosis immune effects." (PMID 38397085, 2024). "Additionally, we analyzed the previously reported RNA dataset of whole lung tissues from tuberculosis patients and uninfected individuals (GSE114911), in which DEFB1 was also found to be upregulated after infection." (PMID 38397085, 2024).
vitiligo (1 paper, 2023). Generalized well circumscribed patches of leukoderma that are generally distributed over symmetric body locations and is due to autoimmune destruction of melanocytes. "The Study of the DEFB1 single nucleotide polymorphism showed that there was a significant predominance of GG genotype in vitiligo patients 37 (74%) and a predominance of the AA genotype in controls (p < 0.001)." (PMID 36535830, 2023). "It seems that DEFB1 gene polymorphism at -20 might modulate vitiligo development risk as the DEFB1 (−20G/A) GG genotype and G allele contribute to vitiligo development in Egyptian populations." (PMID 36535830, 2023). "The serum level of HBD-1 had a non-significant association with DEFB-1 genotypes in vitiligo patients (p = 0.611) or in the control group (p = 0.716)." (PMID 36535830, 2023). "The DEFB-1 genotypes had a non-significant association with all studied personal and clinical data of vitiligo patients (p > 0.05 for all) (data not shown)." (PMID 36535830, 2023).
tumor (63 papers, 2006 to 2025). "The DEFB1 gene, which encodes human ß-defensin-1 (HBD-1), contributes to innate immune responses and functions as a potential tumor suppressor in urological cancers." (PMID 27835705, 2016). "Methylation analysis showed that the beta value of SIAH2 was higher in the tumor group than in the normal group, and DEFB1 was the opposite." (PMID 38393698, 2024). "Only DEFB1 was up-regulated in the tumor group; in contrast, SIAH2 and SYT1 were down-regulated in the low-risk group (Wilcoxon test, P > 0.05)." (PMID 38393698, 2024). "It has also been shown by merging of multiple microarray datasets of differentially expressed genes (DEGs) that DEFB1 is down regulated in 355 OSCC tumor samples compared to 131 normal (healthy) controls." (PMID 31131258, 2019). "Transduction of DEFB1 gene or treatment with recombinant hBD-1 led to inhibition of cell growth and apoptosis of tumor cells." (PMID 24658581, 2014). "Results of a previous study suggested that the DEFB1 gene, which encodes human ß-defensin-1 (HBD-1), plays a role in innate immune responses and may act as a potential tumor suppressor in urological cancers." (PMID 38393698, 2024). "All genes were lowly expressed in tumor samples, except for DEFB1 and SST." (PMID 37318692, 2023). "Typical ones as β-defensin-1 (DEFB1), growth arrest and DNA damage-inducible gamma (GADD45G), HSP70 binding protein 21 (encoded by TTC36) that protect the organism from and down-regulated in HCC or multiple tumor types, were significantly decreased in liver of TG vs. WT pigs." (PMID 34322121, 2021). "Recent research has indicated that DEFB1 participates in the RTK/PI3K/AKT/mTOR pathway, potentially influencing the adaptability and invasion of tumor cells within the TME." (PMID 40881700, 2025). "The eight genes (CAMK2N1, WNT7A, F2RL1, AREG, DEFB1, CNFN, TGFBI, and CAV1) included in the signature have been extensively studied and are known to be involved in tumor progression and EMT process." (PMID 37907576, 2023). "Of the eight IRGs, only DEFB1 and SST were highly expressed in tumor tissues, while the other six genes were lowly expressed." (PMID 37318692, 2023). "As expected, all genes were lowly expressed in tumor tissues of multiple validation data sets, except for DEFB1 and SST, which were highly expressed in tumor tissues." (PMID 37318692, 2023). "This suggests that although tumor stage is a traditional indicator when predicting prognosis, the additional factors in our nomogram, IRGs signatures consisting CCL8 and DEFB1, and the age of patients, are also worth considering." (PMID 32719391, 2020). "DEFB1 inhibits tumor invasion and migration in OSCC, and CTLA4, a negative regulator of T cell activation, has shown efficacy in boosting anti-tumor immunity when targeted with CTLA4 inhibitors." (PMID 39857718, 2025). "For example, DEFB1, the human antimicrobial peptide defensin β 1, is considered as a potential tumor suppressor gene and has been shown to mediate PI3K/mTOR signaling, thereby leading to death of tumor cells." (PMID 35938006, 2022). "Furthermore, it has been observed that DNA methylation pattern within non-CpG island promoter region of DEFB1 can influence epigenetic silencing of DEFB1 in tumor cells." (PMID 38393698, 2024).